PON1 (paraoxonase 1)
Diseases named in the same sentence as PON1 in open-access papers (continued):
Sharing a sentence is not in itself a finding about the gene and the disease.
schizophrenia (12 papers, 2014 to 2024). A major psychotic disorder characterized by abnormalities in the perception or expression of reality. "Concerning oxidative stress, PON1 emerges as a candidate gene implicated in both schizophrenia and T2DM." (PMID 39324122, 2024). "Studies have also reported a significant reduction in the concentrations of HDL–cholesterol, a cholesterol fraction that is critically linked with paraoxonase-1, in patients with schizophrenia." (PMID 37627479, 2023). "Therefore, schizophrenia, and especially deficit schizophrenia, is accompanied by a disbalance in the causome (increased zonulin) versus the protectome (lowered natural IgM and PON1 paraoxonase activity) leading to lowered risk resilience (RR)." (PMID 32957709, 2020). "Therefore, a reduction in paraoxonase-1 concentration might account for a systemic pro-oxidative state as well as the increased cardiovascular risk observed in patients with schizophrenia." (PMID 37627479, 2023). "We searched electronic databases from inception to 31 May 2023 for studies investigating paraoxonase-1 in patients with schizophrenia and healthy controls and assessed the risk of bias and the certainty of evidence (PROSPERO registration number: CRD42023435442)." (PMID 37627479, 2023). "In individuals diagnosed with schizophrenia, there is a notable reduction in PON1 enzyme activity, and this diminishing trend adversely impacts the normal functioning of β-cells." (PMID 39324122, 2024). "Based on the current literature data during the first episode of schizophrenia PON-1 activity is declined and is normalized only after appropriate therapy." (PMID 37511134, 2023). "Our results demonstrate that the lowest level of PON-1 was in patients with schizophrenia, while the control group had higher concentrations." (PMID 37511134, 2023). "In the group of patients with psychosis in the course of schizophrenia, we observed a statistically significant positive correlation between PON-1 activity and serum HDL concentration (r = 0.82, p <0.01)." (PMID 37511134, 2023). "Drug-naïve first-episode patients with schizophrenia show an inverse relationship between decreased activity of the enzyme PON1 and increased cytokine levels, including IL-6, IL-4, and IL-10." (PMID 33315097, 2021). "In humans, the lower levels of paraoxonase 1 enzyme (PON1) activity in schizophrenia, leading to impaired function of the innate immune system and increased oxidative stress, has been linked to increased IgA responses to Pseudomonas putida, Morganella morganii, and Pseudomonas aeruginosa." (PMID 37510410, 2023). "The possible mechanism of the altered lipid profile in schizophrenia may be due to the overlapping risk factors for schizophrenia, the broad spectrum of disease, and redox levels including HDL and PON-1." (PMID 37511134, 2023). "We investigated this issue by conducting a systematic review and meta-analysis of the association between the circulating concentrations of paraoxonase-1, an antioxidant calcium-dependent high-density lipoprotein (HDL)-associated esterase, with paraoxonase and arylesterase activity in schizophrenia." (PMID 37627479, 2023). "Therefore, this study aimed to develop a quantitative system, and investigate the levels of 5-MTHF in schizophrenia patients and healthy controls carrying various PON1 Q192R and MTHFR C677T genotypes." (PMID 36014826, 2022). "PON1 is a candidate for a gene that overlaps schizophrenia and T2DM." (PMID 33315097, 2021). "In the absence of overall between-group differences, our systematic review and meta-analysis suggests that alterations in paraoxonase-1 may reflect a pro-oxidant state in specific subgroups of patients with schizophrenia that require further assessment in appropriately designed studies." (PMID 37627479, 2023).
schizophrenia (continued). "The R variant of PON1 and the T variant of MTHFR C677T were associated with increased homocysteine levels, but whether the variants of PON1 and the variants of MTHFR were indirectly associated with reduced MTHF levels in schizophrenia patients is still unclear." (PMID 36014826, 2022). "We found that individuals with schizophrenia exhibit alterations in lipoprotein levels, particularly decreased HDL and PON-1 activity." (PMID 37511134, 2023). "In our systematic review and meta-analysis, the enzymatic activity of paraoxonase and arylesterase, two essential components of circulating paraoxonase-1, were non-significantly different between patients with schizophrenia and healthy controls." (PMID 37627479, 2023). "Our study has shown the presence of non-significant differences in circulating paraoxonase-1, expressed as paraoxonase and arylesterase enzyme activity, between patients with schizophrenia and healthy controls." (PMID 37627479, 2023). "The correlation between serum HDL concentration and PON-1 activity, as well as the negative correlation with LDL concentration, further the involvement of lipoproteins in the pathophysiology of schizophrenia." (PMID 37511134, 2023). "While the activities and isoforms of PON-1 do not appear to have any relationship to deployment in Gulf War era veterans, lowered PON-1 activities do appear to be a key component in the ongoing nitric oxide stress processes that accompany affective disorders, general anxiety and schizophrenia." (PMID 38167090, 2024).
coronary atherosclerosis (11 papers, 2011 to 2025). Atherosclerosis of the coronary vasculature. "The decreasing PON-1 activity is an independent cardiovascular risk factor and leads to the elevated oxidative stress and promotes progression of coronary atherosclerosis." (PMID 33936387, 2021). "The decreased PON1 activity has been suggested to induce an increased incidence of coronary atherosclerosis." (PMID 39149586, 2024). "The adenovirus-mediated expressions of human PON-1 remarkably reduce the oxidative stress and inflammation in the coronary plaques and prevent the progression of coronary atherosclerosis." (PMID 33936387, 2021). "The overexpressing human PON-1 decreases oxidative stress and proinflammatory response and inhibits the progression of coronary atherosclerosis by decreasing oxidized LDL in plasma and in the coronary plaque." (PMID 33936387, 2021). "Adenovirus-mediated gene transfer of human PON-1 is a potential method to prevent against coronary atherosclerosis in humans." (PMID 33936387, 2021). "The results suggested that the low PON1 activity level was also present for patients with coronary artery atherosclerosis." (PMID 28038449, 2017). "At middle and particularly high tertile of apoA-I glycation, patients with low levels of HDL-associated activities of PON1 and PON3 had approximately 2 to 2.5 fold increased risk for severe coronary atherosclerosis." (PMID 25964115, 2015). "Navab and colleagues reported a failure of HDL to protect LDL from oxidation in patients with coronary atherosclerosis, which they proposed was due to their low serum PON1 activity despite relatively normal HDL-C levels." (PMID 22078494, 2011). "This inference implies that serum PON-1 and SRB-1 could be used as non-invasive tools for the identification of coronary atherosclerosis and risk assessment in CAD cases." (PMID 39336967, 2024). "The use of adenovirus expressions of human PON-1 may be a useful method for preventing coronary atherosclerosis in humans." (PMID 33936387, 2021). "The use of adenovirus expressions of human PON-1 may be a useful method for inhibiting coronary atherosclerosis in humans." (PMID 33936387, 2021).
non-alcoholic fatty liver disease (11 papers, 2012 to 2025). "In this study, we evaluated the antioxidant effect of filtered açai pulp on the expression of paraoxonase (PON) isoforms and PON1 activity in rats with nonalcoholic fatty liver disease (NAFLD)." (PMID 27642496, 2016).
autism (9 papers, 2007 to 2021). Persistent deficits in social interaction and communication and interaction as well as a markedly restricted repertoire of activity and interest as well as repetitive patterns of behavior. "Interestingly, Caucasian-American and not Italian families displayed a significant association between autism and PON1 variants less active in vitro on the OP diazinon (R192)." (PMID 29056653, 2015). "Some studies have also suggested that variants in PON1 may play a role in neuropsychiatric disease such as schizophrenia, depression and autism with mechanisms that are far from being understood." (PMID 29056653, 2015). "In 2005, D’Amelio and coworkers assessed linkage/association between autism and PON1 variants." (PMID 29056653, 2015). "With a reduction in PON1 activity, there is a potential for increasing homocysteine levels which are associated with genome-wide DNA hypomethylation that may carry over from one generation to the next, affecting both neurodevelopment and autism prevalence." (PMID 22490277, 2012). "The PON1 R192 gene variant was implicated in the pathogenesis of autism among North American (Caucasian), but not Italian, organophosphate users." (PMID 32386510, 2020). "In the two articles included in this review, the PON1 108T allele was associated with autism but not significantly." (PMID 32386510, 2020). "We then used the expanded model to compare the U.S. and Italian populations to determine what, if any, factors could explain the difference in PON1 gene variation and autism prevalence between the two countries." (PMID 22490277, 2012). "Inorganic Hg may interact with cysteine residues on PON1 preventing its activation in the liver and impairing the body's ability to protect itself against OP pesticides and oxidative stressors involved in autism." (PMID 22490277, 2012). "Gene variants of paraoxonase-1 are associated with autism in North America, but not in Italy, indicating regional specificity in gene-environment interactions." (PMID 22490277, 2012). "The PON1 gene variants associated with autism in subgroups of the U.S. population but not in Italy could be attributed to the fact that HFCS consumption rarely occurs in Italy, thereby lessening the conditions for PON1 modulation." (PMID 22490277, 2012). "A comparison of common sources of mercury exposure in the U.S. and Italy may offer a further explanation of the PON1 gene variation associated with autism in the U.S. but not in Italy." (PMID 22490277, 2012).
hyperhomocysteinemia (9 papers, 2010 to 2024). A serious metabolic condition caused by mutations in the MTHFR gene, medications, or nutritional deficiency. "Red wine polyphenol extract supplementation to the drinking water of heterozygous Cbs-deficient mice (a murine model of hyperhomocysteinemia) for four weeks increased hepatic Pon1 expression and hepatic and plasma PON1 arylesterase activities." (PMID 28212288, 2017). "In the presence of hyperhomocysteinemia (HHcy) induced by feeding with a high-methionine diet, DJ-1 and Prdx2 proteins were significantly upregulated in HHcy Pon1−/− mice compared to HHcy Pon+/+ animals." (PMID 39594433, 2024). "Pon1 gene deletion affects the expression of cellular proteins in an organ-specific way, with the patterns of expression modulated by hyperhomocysteinemia (HHcy)." (PMID 39594433, 2024). "We also examined the effects of hyperhomocysteinemia (HHcy), induced by providing 1% methionine in drinking water, on the Pon1–Phf8 interaction." (PMID 36899882, 2023). "According to the authors, the lowering of the PON1 activity caused by hyperhomocysteinemia, or complete lack of PON1, as in knockout mice, makes the HDL dysfunctional, which leads to an imbalance in the ADMA and DDAH, resulting in decreased eNOS production." (PMID 31817387, 2019). "Although previous studies had already reported that hyperhomocysteinemia mediates vascular dysfunction by increasing ADMA and down-regulating DDAH2, the implication of PON1 needed to be explained." (PMID 31817387, 2019).
ovarian carcinoma (9 papers, 2012 to 2025). A malignant neoplasm originating from the surface ovarian epithelium. "Studies suggest that PON1 polymorphisms are associated with various cancers including ovarian cancer and its activity was negatively correlated with ovarian tumor size in human subjects providing clinical evidence for a link between PON and cancer." (PMID 29531225, 2018). "We also found a protective SNP that occurs in the PON1 gene (Q192R; rs662) that is known to lower (0.65x) risk for ovarian cancer." (PMID 22938532, 2012). "Genetic variation in PON1 has also been linked to prostate 34 and ovarian cancer." (PMID 29845757, 2018). "It has been suggested before, that SNPs reducing PON1 activity may be associated with an increased risk of epithelial ovarian cancer." (PMID 25265318, 2014). "It was also reported that PON1 genetic variants may alter the risk of epithelial ovarian cancer among smokers and obese women." (PMID 22856521, 2012). "Similarly, PON1 has been implicated in ovarian cancer and it was shown to be involved in a variety of enzymatic activities including lactonase, arylesterase, peroxidase, and phospholipase activities." (PMID 22856521, 2012). "It has been suggested that women who carry PON1 alleles associated with reduced PON1 activity and those with lower concentrations might be at higher risk for developing ovarian cancer." (PMID 22856521, 2012). "We selected haptoglobin and PON1, based on the implication of their glycosylation, in particular the sialylation aberration in ovarian cancer and other cancers." (PMID 22856521, 2012). "These integrated results strongly suggest that haptoglobin, PON1 and zinc-alpha-2-glycoprotein may undergo specific sialylation changes at the glycoeptide level in ovarian cancer." (PMID 22856521, 2012).
vascular dementia (9 papers, 2017 to 2024). A degenerative vascular disorder affecting the brain. "In patients with vascular dementia, the low arylesterase activity of PON1 was associated with increased brain ischemia and medial temporal lobe atrophy." (PMID 39594433, 2024). "Vascular dementia (VaD) and AD were associated with different genotypes at codon 192 of the PON1 gene in that homozygous glutamine-glutamine at codon 192 was associated with VaD, whereas homozygous arginine-arginine was more associated with AD." (PMID 33352859, 2020). "In patients with vascular dementia, a reduction in PON1 arylesterase activity reflected the increase in medial temporal lobe atrophy and brain ischemia." (PMID 37175471, 2023). "Low PON1 arylesterase activity, found in individuals with MCI, has been associated with an increased risk of developing vascular dementia." (PMID 37175471, 2023). "A French study showed that serum PON1 activity was significantly decreased in vascular dementia (VaD) patients, suggesting that PON1 activity may be a biomarker for VaD patients." (PMID 33628379, 2021). "However, the low levels of PON1 activity against this lipid peroxidation may explain pathologies such as late‐onset AD and vascular dementia." (PMID 37772794, 2023). "The authors concluded that PON1 activity and MDA/TBARS markers of oxidative stress were associated with vascular dementia and brain atrophy rather than cognitive decline." (PMID 37175471, 2023).
asthma (8 papers, 2009 to 2025). "Sub-group analysis showed that asthma-associated PON-1 reduction was significant in children (SMD = −1.85, 95% CI 3.11 to −0.59, p = 0.004) but not in adults (SMD = −1.30, 95% CI −2.65 to 0.05, p = 0.06)." (PMID 36344783, 2023). "The lack of information provided in the selected studies on PON-l gene polymorphisms, body mass index (associated with the risk of asthma), and use of specific drugs (e.g., metformin, associated with increases PON-1 activity) represent additional limitations of our study." (PMID 36344783, 2023). "A recently published meta-analysis has shown that serum PON-1 concentrations are significantly lower in patients with asthma, suggesting the presence of an impaired antioxidant defense in this group." (PMID 40298638, 2025). "In the work by Chen and colleagues, PON1 over-expression was protective in a murine model of asthma, decreasing bronchial wall thickness and fibrosis, and reducing inflammatory cells in bronchioalveolar lavage fluid." (PMID 36138190, 2023). "Our meta-analysis has shown that serum PON-1 concentrations are significantly lower in patients with asthma, suggesting the presence of an impaired antioxidant defense in this group." (PMID 36344783, 2023). "We conducted a systematic review and meta-analysis of plasma/serum concentrations of PON-1 in asthma, a chronic inflammatory airway disease." (PMID 36344783, 2023). "Thus, we assessed the immunomodulatory effects of paraoxonase-1 (PON1) on allergic airway inflammation in a mouse model of asthma." (PMID 39684469, 2024). "Recent studies showed that decreased PON1 activity may be involved in the pathogenesis and severity of asthma, suggesting that PON1 can affect the occurrence and development of asthma by reducing inflammation." (PMID 39684469, 2024). "Although the exact mechanisms responsible for the lower serum activity of PON-1 activity in asthma are unclear, the imbalance between excessive production of free radicals and deficiency in antioxidant defence system might play an important role." (PMID 36344783, 2023). "In order to capture and interpret the available evidence regarding the relationship between PON-1 activity and asthma, we conducted a systematic review and meta-analysis of studies reporting plasma/serum concentrations of PON-1 activity in asthmatic patients and control groups." (PMID 36344783, 2023). "Recent studies have shown that PON1 expression and activity were significantly decreased in asthma and may have potential effects on asthma diagnosis." (PMID 32676117, 2020). "Other investigators including a murine model of asthma have previously demonstrated the ability of L-4F to promote anti-inflammatory effects of HDL, including increases in PON1." (PMID 23691230, 2013). "As the selected studies did not investigate the role of PON-1 gene polymorphisms, further research is warranted to investigate interplay between specific PON-l gene polymorphisms, PON-l activity, and asthma." (PMID 36344783, 2023). "There were non-significant differences in PON-1 concentrations in patients with severe vs. mild-to-moderate asthma (SMD = − 0.39, 95% CI − 1.00 to 0.22, p = 0.21)." (PMID 36344783, 2023). "In this study, several genes including Gdpd2, Spon2, Pon1, Scgb3a2, Ighv2-3, Sult1d1, Cyp2f2, Npas2, Arntl, and Igkv4-68 were down-regulated in OVA-challenged mice compared with control mice, may be useful as biomarkers of asthma." (PMID 29086354, 2018).